ERP29 (endoplasmic reticulum protein 29)
Diseases named in the same sentence as ERP29 in open-access papers (continued):
Sharing a sentence is not in itself a finding about the gene and the disease.
glaucoma (1 paper, 2019). Increased pressure in the eyeball due to obstruction of the outflow of aqueous humor. "On the contrary, the proteins HSP90AA1, HSPE1 and ERP29 are mainly functional as molecular chaperone complexes essential for the maintenance of the protein folding and protein trafficking, during cellular stress responses and are a hallmark for various neurodegenerative diseases, including glaucoma." (PMID 31443184, 2019).
ischemic stroke (1 paper, 2021). A stroke disorder caused by obstruction of blood flow to the brain, due to thrombotic (local blood clot formation) or embolic (due to a blood clot or other material traveling from another site) event. "Endoplasmic reticulum protein-29 and CdC-42 were expressed only in endothelial progenitor cells of healthy subjects, and elongation factor-2 was identified only in endothelial progenitor cells from patients with ischemic stroke." (PMID 34948066, 2021).
myeloproliferative diseases (1 paper, 2025). "For example, myeloproliferative diseases (excluding chronic myeloid leukemia, CML) have the most colocalized genes, including RPN1, BRAP, PPP1CC, ERP29, and PARP1." (PMID 41048997, 2025). "Moreover, myeloproliferative diseases (excluding CML) and essential (haemorrhagic) thrombocythaemia have three identical colocalized genes, namely BRAP, PPP1CC, and ERP29." (PMID 41048997, 2025).
ovarian carcinoma (1 paper, 2018). A malignant neoplasm originating from the surface ovarian epithelium. "Expression changes and possible functional impact of ACTN1, MPST, ERP29 and SERPINB6 are reported for several cancers, but not for ovarian cancer." (PMID 29344361, 2018).
Parkinson disease (1 paper, 2020). A progressive degenerative disorder of the central nervous system characterized by loss of dopamine producing neurons in the substantia nigra and the presence of Lewy bodies in the substantia nigra and locus coeruleus. "Thus, alterations in ERp29 function may have implications for cancer cell survival, β-cell demise in T2D, and neuroprotection in Alzheimer’s and Parkinson’s diseases." (PMID 33013490, 2020).
preeclampsia (1 paper, 2013). Preeclampsia is a hypertensive disorder of pregnancy that is characterized by new-onset hypertension with proteinuria presenting after 20 weeks of gestation, and depending on mild or severe forms may initially present with severe headache, visual disturbances, and hyperreflexia. "Moreover, increased expression of ERp29 was detected in the placenta from women with preeclampsia using proteomics analysis and it may relate to the oxidative stress and apoptosis." (PMID 24391750, 2013).
rheumatoid arthritis (1 paper, 2023). A chronic, systemic autoimmune disorder characterized by inflammation in the synovial membranes and articular surfaces. "For example, SPR has been used to determine the affinity of CRT for several of these lectin-independent interactions, including rheumatoid arthritis shared epitope (11 μM), complement C1q (0.5 μM), glycosylated laminin (0.5 μM), ERp29 (13 μM), and ERp57 (23 μM)." (PMID 37979915, 2023).
Salmonella Infections (1 paper, 2024). Infections with bacteria of the genus SALMONELLA. "In the present study, the ERP29 gene expression level was downregulated after Salmonella infection in chicks, and this downregulation was partially reversed by berberine treatment." (PMID 39664055, 2024).
Stroke (1 paper, 2026). Sudden impairment of blood flow to a part of the brain due to occlusion or rupture of an artery to the brain. "Of these, 5 proteins (ACOX1, BRAP, ERP29, FGF5, and FURIN) also showed strong colocalization with CAD and/or stroke and all had concordant direction of effects for BP and CAD and/or stroke." (PMID 41065563, 2026).
synovitis (1 paper, 2020). Inflammation of a synovial membrane. "Although ERp29, PDIA4, Protein ERGIC-53 and GANAB proteins were highly positively correlated in our work with the histological inflammatory score, their presence and their role in the pathophysiology of synovitis have not yet been described." (PMID 32887899, 2020).
Type 2 Diabetes (1 paper, 2020). "Its significant role in secretory tissue makes ERp29 a potential target for treatment of A1AT deficiency, diseases of thyroglobulin processing, and Type 2 Diabetes." (PMID 33013490, 2020). "Future studies should aim to further elucidate ERp29’s role in UPR, as this response plays a key role in the underlying pathophysiology of cancer and many other diseases, including those of secretory cells such as the insulin-secreting β-cells in Type II diabetes." (PMID 33013490, 2020).
cancer (21 papers, 2012 to 2025). A tumor composed of atypical neoplastic, often pleomorphic cells that invade other tissues. "Dysregulation of ERp29 is linked to several cancers and may serve as a biomarker for the progression of the tumor." (PMID 39940747, 2025). "Next, we determined if FUMH and ERP29 play a role in the reduction of cancer cell migration and invasion by CIL-102." (PMID 34572494, 2021). "Recently, it has been reported that ERp29 negatively regulates the EMT process in MDA-MB-231breast cancer cells." (PMID 29108263, 2017). "Since there is a broad biological function of ERp29 in gastric epithelial cells, targeting this protein and/or its downstream molecules as a new anti-cancer molecular therapeutic approach need further studies." (PMID 29511484, 2017). "Recent studies have also addressed the role of ERp29 in cancer cell survival against chemo- and radio-therapy." (PMID 25232957, 2014). "Many studies indicated that ERp29 was expressed in a variety of human cancer and it was found to be highly expressed in primary tumors and cell lines." (PMID 22160175, 2012). "The relationship between ERp29 and cancer should also be more thoroughly analyzed." (PMID 37958506, 2023). "Noteworthily, ERp29 overexpression was associated with mesenchymal-epithelial transition (MET) upregulation and epithelial morphogenesis as well as with epithelial-mesenchymal transition downregulation in cancer cells." (PMID 33046743, 2020). "Intriguingly, ERp29 is found to be involved in inducing mesenchymal–epithelial transition (MET) of cancer cells and epithelial morphogenesis implicating its another important role in predisposing cancer cells to survival and metastasis as well." (PMID 28874138, 2017). "Besides, ERp29 may also promote cancer invasion and metastasis by regulating epithelial-mesenchymal transition (EMT)." (PMID 35965326, 2022). "Previous reports showed ERp29 could regulate the expression of downstream protein through DNA methylation, and miR-135a-5p expression can be modulated by its promoter methylation status in cancer cells." (PMID 34667160, 2021). "ERp29 is a novel endoplasmic reticulum protein that is expressed widely in many tissues, playing an important role in protein unfolding, modification and secretion, involved in many pathological conditions, including cancer development and age-related degenerate disorders." (PMID 34667160, 2021). "Furthermore, ERp29 may be exploited as a potential target in cancer therapy since it regulates PI3K/Akt and β-catenin pathways, which are well-established and recognized signaling events associated with malignant transformation." (PMID 28874138, 2017). "Hence, our studies prove a novel function of ERp29\MGMT in cancer cell survival against radiation." (PMID 26420420, 2015). "Hence, targeting the ERp29\MGMT could be an effective strategy to overcome resistance to radiotherapy in cancer." (PMID 26420420, 2015). "The expression of PDIA3, PDIA4, PDIA6, ERP29, and TXNDC5 have also upregulated in most cancer types." (PMID 35965326, 2022). "On the other hands, expression of ERp29 in this cell type increased the nuclear expression of TCF3, a transcription factor regulating cancer cell differentiation." (PMID 29511484, 2017). "ERP29 was involved in the formation of epithelial cells by junction transmembrane proteins, and regulation of the epithelial–mesenchymal transition (EMT) in epithelial cells to influence cancer progression." (PMID 31316127, 2019). "The results were consistent with those in tumor cells, where ERp29 upregulated miR-135a-5p expression and downregulated levels of IL-1β and active form of caspase-1, suggesting that this mechanism is generalized but not cancer specific." (PMID 34667160, 2021). "Nevertheless, whether ERp29 is involved in radioresistance in human cancer has not yet been elucidated." (PMID 22160175, 2012).
tumor (15 papers, 2012 to 2025). "We showed that ERp29 was downregulated in primary GC tumors and the downregulation of ERp29 was associated with tumor stage and grade as well as poor survival of the patients." (PMID 28874138, 2017). "ER protein 29 (ERp29) is abnormally expressed in many neoplasms and plays an important role in tumorigenesis." (PMID 34667160, 2021). "Western blot results also indicated the protein level of ERp29 in tumor tissues was higher than that in non-tumor tissues." (PMID 34667160, 2021). "In conclusion, our study reveals that miR-135a-5p functions as a tumor suppressor by targeting ERp29, which in turn affects proliferation, metastasis, and apoptosis of CRC cells." (PMID 34667160, 2021). "From previous studies, one protein ERP29 was shown to be a tumor suppressor and a chaperone protein, which involves the regulation of primary tumor development and the arrest of cell growth." (PMID 34572494, 2021). "Clinical importance of ERp29 in the prognosis of GC patients was assessed by examining its expression in 148 GC tumor samples and correlation with clinicopathological characteristics and survival of the patients." (PMID 28874138, 2017). "Several studies reported that ERp29 functioned as a tumor suppressor since its expression suppressed tumor formation in mice and was inversely correlated with tumor development in breast, lung and gallbladder cancer." (PMID 28874138, 2017). "In this study, we showed that over-expression of ERp29 in GC cells results in the inactivation of ERK1/2 and AKT phosphorylation, causes mesenchymal–epithelial transition (MET) and suppresses tumor progression." (PMID 29108263, 2017). "A recent study demonstrated that expression of ERp29 in MDA-MB-231 cells suppressed tumor growth in nude mice xenograft model by decreasing the cell proliferative index." (PMID 29108263, 2017). "We further analyzed the pathologic characteristics of the 38 GC cases and found that tumor with high ERp29 expression had inclinations towards smaller tumor size and earlier TNM stage." (PMID 29108263, 2017). "ERp29 is linked to PERK activation and eIF2α phosphorylation resulting in cell cycle inhibition and tumor suppression." (PMID 28628644, 2017). "Recent studies indicated that ERp29 can function as a tumor suppressive protein, which protects cells from stress by inhibiting cell growth and primary tumor formation and preventing signaling pathways that facilitate Epithelial–mesenchymal transition (EMT)." (PMID 29511484, 2017). "In order to clarify the in vivo tumorigenicity function of ERp29, GC cells were injected subcutaneously into the nude mice and tumor formation was monitored." (PMID 29108263, 2017). "And tumor with high ERp29 expression had inclinations towards smaller tumor size and earlier TNM stage." (PMID 29108263, 2017). "Downregulation of ERp29 in GC tumors and its strong correlation with tumor progression and patients’ prognosis merit further efforts to develop it as a diagnostic and prognostic biomarker." (PMID 28874138, 2017). "One study pointed out the tumor suppressive role of ERp29 demonstrated by inhibition of tumor formation in mice xenografts." (PMID 27578920, 2016). "Using the methylation PCR array, we have demonstrated that overexpression of ERp29 resulted in hypomethylation of CpG islands in tumour suppressor genes such as CDH1, p16 and MGMT, thereby leading to upregulation of these genes." (PMID 26420420, 2015). "Our previous studies showed that overexpression of ERp29 significantly increased the expression of tumour suppressors, such as E-cadherin (CDH1), at both mRNA and protein levels." (PMID 26420420, 2015). "In addition to the upregulation of ERp29 expression in tumor tissues, the expression of ERp29 can also be upregulated after ionizing radiation." (PMID 37958506, 2023). "In addition, ERp29 is highly expressed in various tumor tissues, and some researchers have identified ERp29 as a carcinogenesis-related gene." (PMID 37958506, 2023).
tumor (continued). "The results and the data showed that FUMH and ERP29 expression in DLD-1 cells is essential for the implication of oxidative stress ROS and JNK/P300 CBP signaling; this is along with the association that CIL-102 inhibited cell invasion and tumor growth." (PMID 34572494, 2021). "Of the 89 pairs of CRC tissues, 65% (58 out of 89) showed higher expression of ERp29 in tumor tissues compared with adjacent non-tumor tissues, while only 35% (31 out of 89) showed downregulation of ERp29 in tumor tissues compared with adjacent non-tumor tissues." (PMID 34667160, 2021). "ERp29 expression was negatively related to tumor size in GC tissues." (PMID 29108263, 2017). "ERp29, a novel 29-kDa endoplasmic reticulum (ER) protein, belongs to the protein disulfide isomerize (PDI) family and has been reported to be closely associated with the tumor development and progression." (PMID 29108263, 2017). "In contrast, ERp29 expression could also sustain tumor cell survival against genotoxic insults by chemotherapy and radiation therapy." (PMID 28874138, 2017). "Collectively, these data suggest that ERp29 may serve as a tumor suppressor and its downregulation may promote GC development and progression." (PMID 28874138, 2017). "In the present study, we found that ERp29 expression is substantially down-regulated in 38 GC tissues compared with adjacent non-tumor tissues by qRT-PCR, indicating that ERp29 may suppress tumorigenicity in GC." (PMID 29108263, 2017). "in vivo result confirmed that overexpression of ERp29 could inhibit the growth of subcutaneous tumor in nude mice." (PMID 29108263, 2017). "We believe that these findings are helpful to understand the tumor suppressive role of ERp29 in GC and underscore the possibility that ERp29 may serve as a potential anticancer drug target for treatment of GC." (PMID 29108263, 2017). "Furthermore, tumor weights were lower in BGC-823/ERp29 group than that in the group of BGC-823/vector (0.50±0.25g vs. 0.91±0.36g, *P<0.05)." (PMID 29108263, 2017). "It was found that expression levels of ERp29 in tumor specimens were negatively correlated with the PI3K/Akt/GSK3β and Akt-mTOR signaling pathway-activated gene signatures and positively correlated with the PI3K/Akt/GSK3β and Akt-mTOR signaling pathway suppressed gene signatures." (PMID 28874138, 2017). "In summary, this is the first study to date demonstrating that ERp29 may functionally serve as a tumor suppressor in GC." (PMID 28874138, 2017). "Erp29 is expressed at varying levels practically in every tissue, yet its precise role in the pathogenesis of neoplasia remains unknown." (PMID 27578920, 2016). "The authors also suggested that overexpression of ERp29 could indirectly result in activation of genes with tumor suppressive functions, like E-cadherin and spleen tyrosine kinase." (PMID 27578920, 2016). "ERp29 staining, when present, was evident in the cytoplasm of tumor cells." (PMID 22160175, 2012). "Previous study showed that ERp29 plays a role in inhibiting tumor proliferation by affecting the epithelial-mesenchymal transition mechanism, but others reported ERp29 could promote tumor proliferation by counteracting the effect of endoplasmic reticulum stress." (PMID 34667160, 2021). "Furthermore, over-expression of ERp29 could up-regulate the genes with tumor suppressive function, e.g., E-cadherin, cyclin-dependent kinase inhibitor and spleen tyrosine kinase." (PMID 29108263, 2017). "Several ER‐resident proteins (ERp29/PDIA9 and ERp57/PDIA3) were enriched up to ∼ 70% in the cytosolic fraction compared with only ∼ 10% enrichment in non‐tumor controls." (PMID 33710763, 2021). "Tumor nodules formed from DLD-1shERp29 cells had lower expression of Ki-67 compared with that from DLD-1shNC cells, indicating a lower proliferation capacity of DLD-1 cells with low ERp29 expression." (PMID 34667160, 2021).
tumor (continued). "The results showed that there were more apoptotic cells in tumor tissues formed from DLD-1shERp29 cells than that from control DLD-1shNC cells, suggesting ERp29 may inhibit apoptosis of DLD-1 cells." (PMID 34667160, 2021).
infection (2 papers, 2017 to 2023). The state of being infected such as from the introduction of a foreign agent such as serum, vaccine, antigenic substance or organism. "Further investigating the roles of ERp29 in Cx43–mediated GJIC during acute mCoV infection required a cell line that mimics the effects of MHV-A59 infection on Cx43 expression in primary astrocytes." (PMID 36572185, 2023). "Conversely, transfecting cells to increase exogenous ERp29 expression significantly reduced mCoV–induced ER stress as measured by levels of BiP and Xbp expressed by DBT-ERp29 cells, measured post infection." (PMID 36572185, 2023). "By contrast, DBT-ERp29 cells showed only single-cell infections at 6 h p.i. and significantly restricted syncytia formation at 9 h and 12 h p.i., clearly indicating that increased ERp29 attenuated MHV-A59 infection of DBT cells." (PMID 36572185, 2023). "This reduced viral infectivity was associated with ERp29-mediated rescue of Cx43 trafficking to the cell surface and formation of functional gap junction channels, since Cx43 inhibitors reversed the ability of DBT-ERp29 cells to resist infection." (PMID 36572185, 2023). "The current study was designed to understand the systemic interaction of host factors during infection to determine whether the ERp29/Cx43 axis has the capacity to be targeted as a therapeutic approach to inhibit viral replication and its associated cellular dystrophy." (PMID 36572185, 2023). "We then determined if increased ERp29 expression in DBT cells affects mCoV infectivity, by analyzing the size, rate, and degree of syncytia formation induced by host cell–cell fusion as a result of MHV-A59 infection." (PMID 36572185, 2023).
inflammatory myopathies (1 paper, 2022). "In inflammatory myopathies, GRN, MVP and NFYB showed high diagnostic value, while RNF128, ERP29 and KPNA3 showed poor diagnostic value, indicating high inflammation activation but little involvement of protein homeostasis." (PMID 36203997, 2022).
ERP29 also shares sentences with these, for which no sentence is quoted: basal cell carcinoma (2 papers); glioma (2); neurodegenerative disease (2); breast tumors (1); clear cell renal cell carcinoma (1); endometrial cancer (1); gallbladder adenocarcinoma (1); hepatocellular carcinoma (1); Lewy body dementia (1); melanoma (1); myocardial diseases (1); neurodevelopmental disorder (1); oropharynx cancer (1); osteosarcoma (1); rectal cancer (1); thrombocythaemia (1).